EGFR (epidermal growth factor receptor)
Diseases named in the same sentence as EGFR in open-access papers (continued):
Sharing a sentence is not in itself a finding about the gene and the disease.
cancer (continued). "Other evidence suggests that CYP2J2 and EETs, which lead to phosphorylation of the epidermal growth factor receptor and the subsequent activation of downstream phosphoinositide 3-kinase (PI3K)/AKT and MAPK signaling pathways, suppresses apoptosis and up-regulates proliferation in carcinoma." (PMID 20187943, 2010). "Therefore, agents like EGCG which target EGFR, HER2, and HER3 may thus provide an effective strategy for inhibiting the growth of cancer cells that display an overexpression and activation of these receptors." (PMID 19325845, 2008). "We describe here how this has resulted in the development of three mAbs that are now in Phase III clinical trials in various cancer indications: zano-limumab (directed against CD4), ofatumumab (directed against CD20) and zalutumumab (directed against epidermal growth factor receptor, EGFR)." (PMID 18702090, 2008). "The ErbB family (ErbB1/EGFR, ErbB2/HER2, ErbB3/HER3 and ErbB4/HER4) of receptor tyrosine kinases (RTKs) is known to drive both formation and progression of a number of commonly occurring cancers, including breast cancer, due to the normal role of these RTKs in regulating cell growth and survival." (PMID 18841159, 2008). "Previous reports and Cancer Genome Project by Sanger Institute have extensively characterised LKB1 mutations in NSCLC cell lines with KRAS and BRAF mutations, but LKB1 status of EGFR mutant NSCLC cell lines has not been extensively analysed." (PMID 18594528, 2008). "In fact, cancer cells may acquire resistance to EGFR inhibitors by increasing the expression and/or the activity of several signalling proteins downstream to EGFR, including pMAPK, pAkt and VEGF, which represent the major escape pathways for EGFR inhibition." (PMID 18665191, 2008). "Importantly, no functional effects of the TNK2/EGFR interaction have been established in a cancer context to date – and, more importantly, it is not known how aberrant expression of EGFRs often found in cancer cells affects this protein–protein interaction." (PMID 18435854, 2008). "It has been known for over a decade that exogenous EGF stimulates PTHrP gene expression in a human lung SCC and keratinocyte lines, but it has not been determined whether EGFR signalling contributes to cancer-mediated syndromes such as HHM." (PMID 17533397, 2007). "For example, the epidermal growth factor receptor (EGFR, HER1, ERBB-1) signaling pathway plays a role in specific phenotypes including resistance to apoptosis, increased proliferation, mitogenesis, transcription of numerous target genes, and actin reorganization, in several cancers 1,3,4." (PMID 19455256, 2007). "EGFR activation/signaling and hypoxia, unlike the VHL mutation, are characteristic of many cancers." (PMID 17083723, 2006). "The epidermal growth factor receptor (EGFR), including EGFR (Erb-B1), HER2/neu (Erb-B2), HER3 (Erb-B3) and HER4 (Erb-B4), is a family of receptor tyrosine kinases representing ideal therapeutic targets because they play a critical role in cancer proliferation and survival." (PMID 16288303, 2005). "Recently, EGFR-targeted molecular treatment with tyrosine kinase inhibitors, including gefitinib, has shown significant antitumour activity in clinical trials in advanced NSCLC, with early encouraging clinical data reported in cancer of the head and neck, colon, and breast." (PMID 15785737, 2005). "Similarly, pre- and post-treatment skin biopsy results from cancer patients revealed that EGFR signalling was inhibited at doses ⩾150 mg day−1, with no clear dose dependence above this level." (PMID 14760365, 2004). "In addition, the downregulation of IL6-JAK-STAT3 signaling in the high-risk samples was inconsistent with the enrichment of M2-type macrophages, which indicates that non-classical activation of STAT3, such as through the EGFR or inflammasome pathway, is the dominant driver of cancer." (PMID 41601652, 2026).
cancer (continued). "Recent trials comparing EGFR-inhibitors versus vascular endothelial growth factor inhibitors in combination with chemotherapy in RASwt mCRC have indicated benefit from EGFR-inhibitors in left-sided cancers but not in right-sided cancers, albeit not universally." (PMID 40437037, 2025). "Furthermore, this is consistent with the hypothesized role of ADAM6, like other ADAM family members, to serve in autocrine and paracrine transactivation of the epidermal growth factor receptor (EGFR); an oncogene acting as key player in cancer development and progression." (PMID 40382561, 2025). "However, their experimental set-up of cytotoxicity assays may be incomplete since the authors did not include control experiments using cancer cells in which EGFR expression was knocked down/out." (PMID 40243928, 2025). "Our findings indicate that cancer cells in the high ST6GAL1 expression group interact with M1 macrophages, Breg, and CD8+ T cells via HEBP1−EGFR, YARS−EGFR, and ICAM1−EGFR, suggesting that CRC patients with high ST6GAL1 expression may benefit from anti‐EGFR therapy." (PMID 40847469, 2025). "By definition, chemotherapy targets proliferating cells, so it is conceivable that, while the majority of cancer cells are inhibited by gefitinib, carboplatin and pemetrexed exert a stronger effect on the subpopulations of cells whose growth is not, or only poorly, affected by the EGFR-TKI." (PMID 40846697, 2025). "Furthermore, it would argue that approaches to inhibit YAP/TAZ could promote YAPon-to-YAPoff cancer conversion in certain circumstances, such as combining YAP/TEAD inhibitors with EGFR inhibitors in NSCLC, which has been suggested as a potential therapeutic strategy." (PMID 40440076, 2025). "However, we found no change on the protein level of B7-H3 in EGFR-silenced cell lines, suggesting that B7-H3 may stabilize EGFR signaling for downstream signaling cascade activation to enhance cancer cell growth and metastasis." (PMID 38370387, 2024). "Additionally, patients with these cancers do not benefit from anti-EGFR therapy." (PMID 39263130, 2024). "Besides, we observed an IL-6-induced proliferation in R-TMX cells, which has been reported in cancer cells that do not respond to estrogen; this induction could be regulated through the epidermal growth factor receptor (EGFR)." (PMID 39201674, 2024). "Together, our findings unveil a complex web of molecular alterations that may impact the therapeutic susceptibility of KRAS and EGFR-mutant non-Sq NSCLC across different ancestry groups and consequently may contribute to molecular underpinnings of cancer disparities." (PMID 39033203, 2024). "EGFR is a major oncogenic promoter in human cancers, especially upon gene amplification and overexpression; however, AS43 do not carry EGFR mutations or elevated expression, so we posited that the presence of G842C‐PlxnB2 might promote its noncanonical activation." (PMID 36722641, 2023). "Based on the tight tangling between uPAR signaling and cancer, JAK inhibitors might be potential anti-cancer repurposing drugs when used in combination with chemotherapy, radiotherapy, immunotherapy or other targeted agents (e.g., the EGFR inhibitor Erlotinib)." (PMID 37895906, 2023). "Therefore, the majority of EGFR positive cancers do not respond to TKIs or to mAb." (PMID 37170144, 2023). "AKT control of PD-L1 traffic was similar in non-transformed and transformed cells and it was unaffected by whether the driver oncogene was mutant EGFR or KRAS, indicating this is a fundamental feature of PD-L1 biology and not specific to cancer cells or specific driver mutation." (PMID 36915197, 2023). "Finally, in cancer cells, β integrin subunits are known to interact with a variety of growth factor receptors including the hepatocyte growth factor receptor c-Met, vascular endothelial growth factor receptor-2 (VEGFR-2), epidermal growth factor receptor (EGFR) and the ErbB2 receptor." (PMID 37173970, 2023).
cancer (continued). "However, the molecular features of EGFR‐LFD have not been studied in the Asian cancer population." (PMID 36622089, 2023). "Comparison of DepMap cancer cell line drug sensitivity data with exon 17b inclusion and exclusion junction expression revealed that exon 17b inclusion correlates with increased sensitivity to EGFR inhibitors, represented by a negative correlation with drug area under the curve (AUC)." (PMID 36880935, 2023). "Similarly, regarding the combined carcinoma, researchers have reported that C-NEC has common EGFR mutations in both NEC and non-NEC components, suggesting that these two components may originate from cells of the same origin." (PMID 38067352, 2023). "Therefore, dual inhibition of EGFR and ERBB3 may better prevent treatment-refractory cancer progression as opposed to solely targeting EGFR, especially in tumors overexpressing DARPP-32." (PMID 34675407, 2022). "Thus, we speculate that murine STAP-2 enhances EGFR-independent cell proliferation and does not affect EGFR signaling in murine cancer cells." (PMID 36410436, 2022). "Similarly, 4-1BB agonism on NK cells and the resulting strengthened ADCC showed to augment the efficacy of EGFR- or human epidermal growth factor receptor 2 (HER2)- targeted antibodies, cetuximab and trastuzumab, respectively, in cancers that may have been refractory or unresponsive to monotherapy." (PMID 36185242, 2022). "However, every cancer has a different antigen expression profile and not all tumors express EGFR." (PMID 36185287, 2022). "Therefore, mAb806 can bind to EGFR overexpressed in cancer cells, but not in normal cells." (PMID 36551506, 2022). "While the reason for this increased metastatic potential for HER2+ cancer is likely multifactorial, it has been posited that the driving factors of BCBM in this subtype may be attributed to interactions between HER2 and other receptors, including epidermal growth factor receptor (EGFR) and HER3." (PMID 35327469, 2022). "In addition to physical and chemical characterization, we also showed that PIA-NC induces selective reactive oxygen species surge and apoptosis in response to sublethal near-infrared light only in EGFR-overexpressing cancer cells, not in EGFR-negative fibroblasts." (PMID 36291827, 2022). "An intriguing side effect of Grb2 phosphorylation as a potential negative regulator is that tyrosine kinase inhibitors, such as those widely used as cancer therapeutics in EGFR-driven cancers, could also inhibit this negative regulatory mechanism—conceivably interfering with their desired effects." (PMID 35507881, 2022). "Since ctDNA concentration could be high in plasma samples from more advanced-stage tumors in theory, further studies should be planned to clarify the performance of the EGFR-LAMP liquid biopsy system for advanced cancers through comparisons with negative control groups." (PMID 35744511, 2022). "Similarly, Li and colleagues also compared the relative uptake of cetuximab-functionalised gold nanoparticles (AuNPs) by EGFR-expressing A431 and EGFR-negative MDA-MB-453 cancer cells, using transmission electron microscopy (TEM); they found more AuNPs bound and accumulated in A431 cancer cells." (PMID 34683944, 2021). "Furthermore, activated EGFR via tyrosine phosphorylation at Y1068 initiates downstream signaling pathways, resulting in signal transducer and activator of transcription 3 (STAT3) activation that directly regulates cancer cell proliferation, metastasis, and angiogenesis." (PMID 34445110, 2021). "There is no doubt that a deeper understanding of the interaction between CD44 and EGFR in cancer progression will provide better approaches to cancer treatment, and that combined EGFR/CD44 targeting may be the future direction in the treatment of some types of cancer." (PMID 33981532, 2021).
cancer (continued). "Moreover, analyzing the hsa-miR-205-5p and miR-143-3p target genes, we found several related cancer pathways, including senescence and autophagy, signaling by EGFR in cancer, microRNA regulation of DDR among others, but no genes were shared between these two miRNAs." (PMID 34681793, 2021). "Consequently, EGFR was lowly expressed in the cancer group versus the normal group in LUAD without a statistical difference (P-value: 0.19) and this expression pattern was similar to ESR1 (P-value: 0.42), MYC (P-value: 0.067), RELA (P-value: 0.058) and SMAD3 (P-value: 0.13)." (PMID 33506873, 2021). "However, predicted growth effects in cancer tissues may not be mediated solely by the upregulation of EGFR." (PMID 34799560, 2021). "However, the presence of a relatively higher number of tAuNRs than uAuNRs in EGFR-negative cancer cells may be due to a change of surface charge on AuNRs following functionalisation, which might affect their internalisation." (PMID 34683944, 2021). "Furthermore, since cancer patients with KRAS mutations do not benefit from anti-epidermal growth factor receptor (EGFR) monoclonal antibodies, KRAS mutation testing can guide anti-EGFR therapy selection." (PMID 33467412, 2021). "A combination of curcumin and dasatinib also resulted in the downregulation of the EGFR/IGF-1R/Akt axis, further providing evidence that this may be one of the primary mechanisms of inhibition by curcumin either alone or in synergistic combination with other anti-cancer agents." (PMID 34867402, 2021). "For example, cancer cell growth is regulated by growth hormone receptors, whose amounts are controlled by endocytosis; activated receptor tyrosine kinases (RTK)-ligand complexes, e.g., EGFR-EGF, could activate its downstream targets, such as MEK–ERK pathway, to promote cell growth." (PMID 34552618, 2021). "Notably, we observed a higher expression of GZMB and genes involved in T cell activation in TRM-like cells from EGFR-WT than in those from EGFR-MT, indicating that TRM-like cells in EGFR-WT tumors have the highest antitumor activity for the direct killing of cancer cells." (PMID 34663810, 2021). "The epidermal growth factor receptor (EGFR) kinase family consists of four receptors [ErbB1/EGFR, ErbB2/human epidermal growth factor receptor (HER) 2, ErbB3, and ErbB4] that play a crucial role in cell proliferation, differentiation, and motility and may lead to cancer development." (PMID 36045702, 2021). "Unexpectedly, in some cancer cell subclones, resistance to anti-EGFR therapy might not be entirely mediated by EGFRvIII-positive DMs; rather, resistance might occur through other compensatory mechanisms, such as the potential oncogenic roles of extrachromosomal MDM2 amplification." (PMID 32928268, 2020). "Therefore, locally elevated estrogen formation affects the development and progression of cancer tissues and cells (HCC, HepG2) by activating the rapid signalling pathway mediated via amphiregulin (AREG; a member of the EGF family), a ligand of EGF-R (epidermal growth factor receptor)." (PMID 32290381, 2020). "Moreover, EGFR expression levels in IBCs have not been shown to correlate with cancer responsiveness and recent data have suggested that EGFR mRNA is not frequently overexpressed as previously reported but surprisingly mainly underexpressed compared with normal tissues." (PMID 32377505, 2020). "However, the effects of CD148 on EGFR in certain cancers have not yet been reported." (PMID 32201537, 2020). "In this light, the activation of TRPV1 in the presence of PI3K/Akt and Ras/Raf/MEK/ERK pathway inhibitors—potentially including P2Y2 and EGFR antagonists—may promote cancer cell apoptosis through [Ca2+]i signaling without the induction of proliferative mechanisms." (PMID 32545311, 2020).
cancer (continued). "Sequestration of growth factors by D3 allows erlotinib to be effective at therapeutic serum concentrations in Hep3B cells, which possess wild-type EGFR, reducing the IC50 values from 4.4 uM to 0.2 uM, so D3 addition may broaden erlotinib therapy in non-mutated EGFR cancers." (PMID 32066763, 2020). "Studies have shown that increasing EGFR activity can over-activate downstream pro-oncogenic signaling pathways (e.g., RAS-RAF-MEK-ERK MAPK, and AKT-PI3K-mTOR pathways), which can then activate many biological outputs that may contribute to cancer cell proliferation." (PMID 33362865, 2020). "Hence, targeting tyrosine kinase receptors, for example by the anti-EGFR antibodies nimotuzumab and cetuximab, and the EGFR inhibitors afatinib, erlotinib, and gefitinib, results in enhanced expression of MHC-I and APM components in different cancer cell lines as well as in cancer patients." (PMID 32630675, 2020). "As discussed in the section above, EGFR might have a role not just in regulating its own incorporation in EV compartments, but also that of other proteins involved in its signalling network, particularly in cancer, where it is deregulated." (PMID 33302515, 2020). "However, the intersection of immunology and cancer biology creates challenges whereby a single genomic driver or biomarker (for example BRAF, KIT, or EGFR mutations in targeted therapies) do not adequately explain or predict response among patients being treated with anti-PD1 therapies." (PMID 32708981, 2020). "EGFR signaling in invadopodia might be also sustained by a high level of heparin-binding (HB)-EGF, which is synthesized as pro-HB-EGF and subsequently cleaved by ADAM-12 to release a soluble form binding to EGFR, providing an advantage for cancer cells to intravasate, invade and metastasize." (PMID 33178698, 2020). "The realization that EGFR possesses pro-survival functions independent of its kinase activity over the past decade has opened a new window for a better understanding the role of EGFR in cancer and offered a novel approach of targeting this powerful oncogene for cancer therapy." (PMID 31508364, 2019). "However, it currently remains unclear whether spironolactone exerts combinational effects with non-DNA-damaging anti-cancer drugs, such as gemcitabine and epidermal growth factor receptor tyrosine kinase inhibitors (EGFR-TKIs)." (PMID 31614999, 2019). "We analyzed EGFR-mutated NSCLC patients (n = 24) who were positive or negative for EGFR mutations in cfDNA and compared the results with a second cohort of 24 patients bearing KRAS-mutated cancer, which served as a representative control population not exposed to targeted therapy." (PMID 31861832, 2019). "Thus, blocking the EGFR TK activity by our chalcones may not be able to completely inhibit the A549 cancer cell proliferation." (PMID 30897725, 2019). "However, it was not clear how EGFR regulated P-gp expression in cancer cells." (PMID 31215501, 2019). "The hypothesis of ADCC as additional or alternative anti-cancer mechanism is supported by two mirror observations: i) a small percent of KRAS mutated mCRC patients respond to cetuximab and, ii) not all “all RAS” wt mCRC patients respond to anti-EGFR therapy." (PMID 31500586, 2019). "In addition, the serum NLR was not correlated with the outcomes of ICI treatment in EGFR‐mutated NSCLC, although the serum NLR was reported to be a potent biomarker according to the benefit of ICI treatments in patients with advanced‐stage cancer." (PMID 30790471, 2019). "As the target of both cetuximab and AG1478 is EGFR, a receptor physically recognized and interacted by AREG, it remains unclear whether pharmaceutically targeting AREG with a target‐specific antibody is more effective in minimizing the acquired resistance of cancer cells." (PMID 31493351, 2019).